NF1 (neurofibromin 1)
Diseases named in the same sentence as NF1 in open-access papers (continued):
Sharing a sentence is not in itself a finding about the gene and the disease.
glioma (continued). "However, comprehensive profiling of additional genetic alterations beyond NF1 has not been widely performed and definitive epigenetic classification of gliomas arising in the setting of NF1 has not been reported." (PMID 35945463, 2022). "NF1 patients with gliomas do not show the involvement of specific NF1 gene regions." (PMID 35008787, 2021). "In a mouse model, proliferation of malignant glial tumor cells has been shown to depend on MEK as well as PI3K signalling pathways and manifestation of tumors does not depend on a particular germline pathogenic NF1 variant." (PMID 33863389, 2021). "Similarly, although we identified increased secretion of PDGF-AA in two glioma cell lines as well as immortalized normal human astrocytes upon NF1 knockdown, this relationship was not preserved in the TCGA data." (PMID 29643433, 2018). "While mice with a germline Nf1 gene mutation (Nf1+/− mice) do not develop gliomas, neither do mice in which both copies of the Nf1 gene are inactivated in neuroglial progenitors, suggesting that bi-allelic Nf1 gene inactivation in the proper cell of origin is not sufficient for glioma formation." (PMID 28066715, 2016). "Furthermore, ectopic expression of CREB in T98G cells enhanced the transcriptional activity of the NF1 promoter containing the wild-type CRE but not a mutated one, suggesting that NF1 is directly regulated by CREB in glioma cells." (PMID 23185366, 2012). "In addition to CREB and NF1, previously established targets of miR-9 in glioma stem cells, such as CAMTA1 and JAK1/2, might contribute to the function of miR-9 in glioma cells, although further investigation will be required." (PMID 23185366, 2012). "Similarly, Trametinib forms the backbone of several ongoing glioma clinical trials in combination with the BRAF inhibitor, dabrafenib (GSK-2118436), including pediatric patients with newly diagnosed HGG (NCT03919071) and NF1-LGG or LGG with RAS pathway aberrations (NCT03363217)." (PMID 36730269, 2023). "Current studies have identified a clear role for targeted therapies in tumors harboring the common molecular alterations, but there are limited options for those with non-BRAF or NF-1-altered tumors, such as FGFR-altered glioma." (PMID 40422539, 2025). "Since there were no low-grade glioma cell lines that simulated NF1-OPG, they utilized Adenovirus-Cre (Ad5-Cre) and NF1flox/flox astrocytes to generate NF1-/- astrocyte and microglia cultures." (PMID 38318325, 2023). "In the case of NF1, the diagnosis of OPG is based on its characteristic appearance of glioma on MRI and does not require histological proof." (PMID 36612052, 2022). "In contrast to the glioma cohort, there were no statistical significant differences in overall survival between ALT-positive and ALT-negative NF1-MPNSTs (p = 0.20)." (PMID 31462295, 2019). "Importantly, we detected higher level of FOSL1 mRNA in the cohort of IDH-wt gliomas with NF1 alterations (Student’s t test p=0.018), as well as a significant negative correlation between FOSL1 and NF1 mRNA levels (Pearson R = −0.44, p=7.8e-12)." (PMID 34399888, 2021). "(B) Frequency of NF1 alterations in MES and non-MES IDH-wt gliomas." (PMID 34399888, 2021).
neurofibromatosis (321 papers, 2003 to 2026). A hereditary neoplastic syndrome in which tumors grow in the nervous system. "The neurofibromin 1 (NF1) splice-site mutation c.61-2A>G (rs1131691100) is a rare, pathogenic, autosomal dominant variant that disrupts NF1 tumor-suppressor function, causing neurofibromatosis type 1 (NF1)." (PMID 41683605, 2026). "Malignant peripheral nerve sheath tumors (MPNSTs) are aggressive sarcomas that constitute a major cause of mortality in individuals with neurofibromatosis type 1 (NF-1) and exhibit highly variable responses to radiotherapy." (PMID 41766655, 2026). "Neurofibromatosis type 1 (NF-1) is the most common phakomatosis with autosomal dominant inheritance, caused by mutations in the NF-1 gene on chromosome 17q11.2, which codes for neurofibromin protein, a negative regulator of the RAS/MAPK pathway." (PMID 41185817, 2025). "It is well known that neurofibromatosis is a disease caused by a mutation in the NF-1 gene, located on chromosome 17q11.2, following an autosomal dominant inheritance pattern." (PMID 40563584, 2025). "NF1 is a tumor suppressor gene, and loss of the wild-type allele is observed in malignancies associated with neurofibromatosis." (PMID 40402550, 2025). "Neurofibromatosis type 1 (NF1; MIM 162200) is an autosomal dominant disorder caused by germline variants of the NF1 gene." (PMID 40410838, 2025). "Historically, several reports have associated neurofibromatosis with macrodactyly (primarily affecting NF1 and, even more rarely, NF2)." (PMID 40126231, 2025). "Neurofibromatosis type 1 (NF1) is caused by loss-of-function (LOF) mutations in the NF1 gene encoding a negative regulator of the RAS signaling pathway." (PMID 41223283, 2025). "NF1 c.888+1G>A is a well-established pathogenic variant that has been reported in numerous patients with neurofibromatosis in the literature, consistent with the RNA findings indicating a deleterious splice defect." (PMID 41300834, 2025). "Schwannomas of the GIT are mostly benign origin, but under certain conditions they also have malignant potential, e.g. in some genetic diseases such as neurofibromatosis (type 1 + 2), when the tumor suppressor genes NF1 and NF2 are mutated." (PMID 40678162, 2025). "Neurofibromatosis type 1 (NF-1) is a genetic disorder caused by a mutation in the NF-1 gene on chromosome 17." (PMID 40710016, 2025). "Neurofibromatosis type 1 (NF1) is a multi-system, autosomal dominant genetic disorder driven by the systemic loss of the NF1 protein neurofibromin." (PMID 40291747, 2025). "Only 1–2% of all GIST cases occur in patients carrying a mutation in the NF-1 gene, which is responsible for neurofibromatosis." (PMID 40563584, 2025). "In 2021, the International Consensus Group of Diagnostic Standards for Neurofibromatosis proposed revisions of the NF-1 diagnostic standard (1987) mainly incorporating genetic diagnosis." (PMID 41170329, 2025). "Regarding focality, four cases had synchronous tumors, including one associated with neurofibromatosis type 1 (NF1) (case #83)." (PMID 39199677, 2024). "Women with Neurofibromatosis Type I (NF1)–a tumor predisposition syndrome caused by a germline NF1 mutation–have an increased risk of developing aggressive breast cancer with poorer prognosis." (PMID 38799507, 2024). "Such individuals harbor mutations in single genes, resulting in clinical syndromes, such as neurofibromatosis, driven by NF1 mutation or microdeletion, for example, 22q11.2 syndrome and teratogen-caused embryopathy." (PMID 39061473, 2024).
neurofibromatosis (continued). "Neurofibromatosis type 1 (NF-1) is associated with vascular complications, including stenosis or the occlusion of the abdominal aorta and renal arteries." (PMID 39726461, 2024). "It occurs due to the mutation in the NF1 gene and the patients present with the phenotypic features of both Neurofibromatosis and Noonan syndrome." (PMID 37602003, 2023). "Literature regarding the malignant schwannoma of the sciatic nerve associated with neurofibromatosis-1 (NF-1)." (PMID 38013269, 2023). "Neurofibromatosis type 1 (NF1) is a common genetic condition arising from pathogenic variants in the NF1 gene on chromosome 17." (PMID 37509275, 2023). "RNF135 has been associated with ASD and neurofibromatosis and reported to be involved in intronic Alu-mediated recombination in NF1 patients." (PMID 37108679, 2023). "Here, a 7-year-old Iranian girl is described with Neurofibromatosis-Noonan syndrome due to a pathogenic variant in NF1 gene." (PMID 36803953, 2023). "Neurofibromatosis type 1 (NF1; MIM#162200) is a neurocutaneous disorder caused by loss-of-function mutations in the neurofibromin-1 (NF1) gene." (PMID 37686382, 2023). "Similar insertions have also been reported to be involved in pathogenic deletions of NF1 in neurofibromatosis." (PMID 37578974, 2023). "The NF1 gene, highly related to neurofibromatosis, encodes neurofibromin, a tumour suppressor protein that acts as a negative regulator of the Ras/MAPK and PI3K/mTOR signalling pathways." (PMID 37892022, 2023). "An example of a dual diagnosis in our cohort is patient GC030951, with both 22q11.2DS and a pathogenic variant in the NF1 gene resulting in Neurofibromatosis as well as 22q11.2DS." (PMID 36980952, 2023). "Intrathoracic meningoceles (IM) are quite rare; they are commonly associated with neurofibromatosis type 1 (NF-1)." (PMID 36348911, 2022). "Neurofibromatosis type 1 (NF1) is an autosomal dominant disorder associated with the NF1 gene, which encodes the protein neurofibromin." (PMID 35163523, 2022). "For example, neurofibromatosis type 1 (NF1) mutations generated different proportions of mutated transcripts i.e., transcripts containing the exon with the original mutation and those with skipped exon." (PMID 36553628, 2022). "For some diseases, cryptic splicing variants are in fact very common such as POLR3A variants for recessive spastic ataxia, ATM variants for Ataxia telangiectasia, ABCA4 for Stargardt diseases, and NF1 variants for neurofibromatosis." (PMID 34591693, 2022). "The mesenchymal type shows high expression of chitinase-3-like protein 1 (CHI3L1) and tyrosine-protein kinase Met (c-Met), with neurofibromatosis type 1 (NF1) mutation/deletion or low expression of NF1." (PMID 35267480, 2022). "Neurofibromatosis type 1 (NF-1) is an autosomal dominant disease with an incidence of 1 in over 3000 births arising from mutations in the neurofibromin-encoding gene, NF1." (PMID 35628517, 2022). "Multiple tumors are a hallmark of neurofibromatosis type 1(NF1) and related forms, NF2-related-schwannomatosis (formerly NF2) or SMARCB1/LZTR1-related schwannomatoses." (PMID 35741273, 2022). "A 30-year-old female with family history of cancer who has café au lait spots was assessed and found to have a variant in NF1 gene associated with neurofibromatosis." (PMID 35123515, 2022). "The three forms of neurofibromatosis, namely NF1, NF2, and SWN are caused by distinct mutations in specific genes." (PMID 35053664, 2022). "Neurofibromatosis type 1 (NF-1) is a genetic disorder associated with dermatological, musculoskeletal, and neurological features." (PMID 35186543, 2022). "Through in-vitro modeling, a novel NF1 p.L2467 frameshift (fs) mutation identified in a relapsed/refractory Ph-like B-ALL patient with neurofibromatosis demonstrated cytokine independence and increased RAS signaling, indicative of leukemic transformation." (PMID 35515133, 2022).
neurofibromatosis (continued). "Her examination findings were suggestive of neurofibromatosis, hence NF1 mutational analysis was done in tumor tissue." (PMID 35490251, 2022). "Mutations in the NF1-encoding gene lead to an autosomal dominant syndrome, neurofibromatosis, with an incidence of 1 out of 3000 newborns." (PMID 35628517, 2022). "Neurofibromatosis type 1 (NF1) is a common inherited disorder caused by mutations of the NF1 gene that encodes the Ras-GTPase activating protein neurofibromin, leading to overactivation of Ras-dependent signaling pathways such as the mTOR pathway." (PMID 34576341, 2021). "Neurofibromatosis type 1 (NF1) is a complex autosomal dominant disorder associated with germline mutations in the NF1 tumor suppressor gene." (PMID 33530415, 2021). "Pain and inflammation are known to be dysregulated in Neurofibromatosis, however it is unclear how NF1 deficiency exacerbates these symptoms." (PMID 33436083, 2021). "Neurofibromatosis type 1 (NF1) is a complex neurocutaneous disorder caused by loss of function variants and microdeletions in the NF1 gene coding for the protein neurofibromin." (PMID 33853649, 2021). "Neurofibromatosis type 1 (NF1), an autosomal dominant and multisystem disorder, is generally considered to be caused by NF1 inactivation." (PMID 34344877, 2021). "Neurofibromatosis type 1 (NF1) is an autosomal dominant genetic syndrome caused by mutations in the NF1 gene." (PMID 31793149, 2020). "Neurofibromatosis type 1 (NF1) is a common autosomal dominant disorder caused by inactivating mutations in the tumor suppressor gene NF1 and affects roughly 1/3000 newborns worldwide." (PMID 32182803, 2020). "Mutations in human LZTR1 have been linked with schwannomatosis, a form of neurofibromatosis, a neurological disorder associated with sleep problems, mental disabilities, and psychiatric disorders that can also be caused by mutation of the Nf1 gene." (PMID 32339168, 2020). "This locus is associated with growth phenotype lambda and Bayley phenotype Adaptive and is contiguous to the NF1 gene (neurofibromatosis), and therefore implicated in growth in the neural system." (PMID 33270668, 2020). "Through conventional genetic evaluations, germline variants were identified first, such as NF1 for neurofibromatosis and NSD1 for Sotos syndrome." (PMID 32778138, 2020). "To better understand how mutations of the underlying gene (NF1) drive behavioral alterations, we have examined grooming in the Drosophila neurofibromatosis 1 model." (PMID 32697780, 2020). "The aim of this study was to compare the ASD symptom profile of three distinct RASopathies associated with both gain-of-function and loss-of-function mutations: neurofibromatosis type 1 (NF1), Noonan syndrome (NS), and cardiofaciocutaneous syndrome (CFC)." (PMID 33519543, 2020). "In 1987, a National Institutes of Health (NIH) neurofibromatosis working group delineated distinct diagnostic criteria for NF1 and NF2 based on genetic linkage and clinicopathologic analysis." (PMID 31161239, 2020). "Patients with neurofibromatosis type I (NF-1) are predisposed to these tumors, primarily optic pathway gliomas (OPG)." (PMID 33415075, 2020). "NF1 is the most common of all neurofibromatosis syndromes and is caused by the loss of function of NF1 gene (a known tumor suppressor) due to mutation or deletion." (PMID 32098059, 2020). "Gene-based analysis identifies exome-wide significant (P = 2.04 × 10−6) enrichment of damaging de novo mutations in NF1, a gene primarily linked to neurofibromatosis, in infantile spasm." (PMID 31175295, 2019). "All women aged 30–69 with a confirmed NF1 gene variant followed at the Elisabeth Raab Neurofibromatosis Clinic (ERNC) in the University Health Network (UHN) are offered an HR-OBSP referral." (PMID 31121919, 2019). "This type of neurofibromatosis is characterized by genetic alterations on NF1 gene, which had more than 60 exons, and encodes neurofibromin, a tumor suppressor that downregulates the RAS/RAF/MEK/ERK pathway." (PMID 35582147, 2019).
neurofibromatosis (continued). "Strikingly, neurofibromatosis type-1 (NF1) patients, in whom neurofibromin is often mutated or truncated, experience idiopathic chronic pain for which opioids often fail to provide relief." (PMID 30364788, 2018). "•Neurofibromatosis type 1 (NF-1) is often associated with various orthopedic disorders, especially scoliosis." (PMID 30408738, 2018). "Even though women with neurofibromatosis (germline NF1 mutations) have a substantially increased breast cancer risk at a young age and NF1 is commonly mutated in sporadic breast cancers, we have a limited understanding of the role of NF1 in breast cancer." (PMID 30182054, 2018). "Even though it is known that neurofibromatosis patients have a significantly increased breast cancer risk and that NF1 is mutated in sporadic breast cancers, the impact of NF1 deficiency and RAS deregulation in sporadic breast cancer is often overlooked." (PMID 30182054, 2018). "Somatic mutation in NF1 was observed in 8 of 10 of MPNST from patients with neurofibromatosis and 1 of 2 sporadic cases." (PMID 29118384, 2017). "Neurofibromatosis type 1 (NF-1) is an autosomal dominant genetic disease, caused by NF1 gene mutations at chromosome 17q11.2." (PMID 28166752, 2017). "Germline and somatic loss of NF1 in neurofibromatosis patients cause malignant peripheral nerve sheath tumours and GISTs." (PMID 28061772, 2017). "Previously only nine patients with ACC have been found to also have neurofibromatosis in the literature and recently a novel germline frame shift mutation (c.5452_5453delAT) in exon 37 of the NF1 gene was described in one such patient." (PMID 26984275, 2016). "This corroborates the finding that patient’s with Costello Syndrome (HRAS germline mutation), Noonan Syndrome (NRAS, KRAS, PTPN11 germline mutations) and Neurofibromatosis (NF1 germline mutation) all have increased risk of developing fusion-negative RMS." (PMID 25768946, 2015). "Since the identification of the first RASopathy, neurofibromatosis type 1 (NF1), which is caused by inactivation of neurofibromin 1, several other syndromes have been associated with mutations in the core components in the Ras-MAPK pathway." (PMID 26203125, 2015). "Hepatic angiosarcoma has also been associated with anabolic steroids, hemochromatosis, and neurofibromatosis (NF-1)." (PMID 25815217, 2015). "Clinical presentation of neurofibromatosis and Noonan syndrome often overlaps and recent studies have implicated a mutation in NF1 gene in the etiology of NFNS." (PMID 23691379, 2013). "The relatively high levels of active Ras.GTP that occur in NF1 deficient cells contribute to neurofibromatosis and to cancer in NF1−/− patients." (PMID 22776759, 2012). "There has also been a report of bilateral mandibular lesions in association with neurofibromatosis and a mutation in the NF1 gene, which is associated with neurofibromatosis and with Noonan Syndrome." (PMID 22640403, 2012). "Mutations in the NF1 tumor suppressor gene cause neurofibromatosis type 1 (NF1), a common chronic debilitating disorder that affects 1 in 3,000 individuals." (PMID 21980365, 2011). "For approximately 72% of the NF1-associated deaths, the underlying cause was coded as a pathology other than neurofibromatosis." (PMID 21439034, 2011). "Perhaps not surprisingly, patients with Noonan syndrome attributed to a mutation at the NF1 gene also have findings consistent with neurofibromatosis." (PMID 22011734, 2011). "Neurofibromatosis in this patient was transmitted by the boy's farther who carried the mutation NF1 c." (PMID 16961930, 2006). "For examples, the insertions cause heamophilia B (factor IX gene), neurofibromatosis (NF-1 gene), Apert syndrome (FGFR2 gene), acholinesterasemia (ChE gene), desmoid tumors (APC gene) and breast cancer (see the review by Kazazian, 1998)." (PMID 12610505, 2003).